CXCR4 (C-X-C motif chemokine receptor 4)
Diseases named in the same sentence as CXCR4 in open-access papers (continued):
Sharing a sentence is not in itself a finding about the gene and the disease.
tumor (continued). "In brief, the engineered bMSCs exposed to hypoxia could effectively transfer the drug to the tumor cells based on the CXCR4/SDF-1α axis." (PMID 34069607, 2021). "[68Ga]Pentixafor positron emission tomography (PET) is a well-established method to image CXCR4 expression of hematopoietic and solid tumors in vivo and previous studies with [68Ga]Pentixafor have revealed a wide heterogeneity of tumor CXCR4 expression within different entities of cancer." (PMID 34417915, 2021). "Uniform results were shown for CXCR4: in agreement with our result, elevated CXCR4 expression was measured in CRC tissues compared with paired normal samples, with the level associated with tumor size, metastasis status, and invasion ability." (PMID 34335790, 2021). "In the treatment of CXCL12/SDF-1α-secreting glioblastoma cells, anti-EGFRvIII CAR NK cells were used with overexpression of CXCR4 and the results showed an increase in chemotaxis towards these tumor cells, complete tumor remission in a number of mice, and an increased overall survival." (PMID 34923966, 2021). "Further evaluation of CXCR4 as a potential imaging biomarker could be warranted for the development of broader anti-tumor therapies." (PMID 34833360, 2021). "Recent findings indicated that CXCR4 expression on tumor cells plays a positive role in key downstream pathways, including PI3K/AKT/mechanistic target of rapamycin kinase (PI3K/AKT/MTOR) and extracellular signal-regulated kinase 1/2 (ERK1/2), which promote tumor proliferation and migration." (PMID 34722241, 2021). "Finally, Cxcr4, a common marker that together with α7-Integrin characterizes SCs and has a role in promoting tumor spread and metastasis, was also observed at similar levels in Ad-Cre FAPs and eRMS cells." (PMID 33671425, 2021). "Tumours initiated with TASCs overexpressing SDC2‐peptide also had lower expression of CXCR4." (PMID 33152121, 2021). "Moreover, CD69 controls T-cell differentiation through its interaction with galectin-148, and TGF-β-triggered CXCL12/CXCR4 signaling has been demonstrated to promote tumor invasion, metastasis, and therapeutic resistance." (PMID 34001881, 2021). "Given its pre-eminent role in the context of tumor cell growth as well as metastasis, the C-X-C motif chemokine receptor 4 (CXCR4) has attracted a lot of interest in the field of nuclear oncology, and clinical evidence on the high potential of CXCR4-targeted theranostics is constantly accumulating." (PMID 34885030, 2021). "Angiogenic tumor vessels were also strongly positive for CXCR4." (PMID 34200145, 2021). "CXCR4/MIF axis positively modulates tumor growth and EMT interaction in NSCLC." (PMID 33314730, 2021). "In addition, we performed Spearman's rank correlation coefficient analysis and found a significant positive relationship between tumor-infiltrating pDC and CXCR-4 expression (r = 0.669, P < 0.01)." (PMID 33854604, 2021). "Preclinical studies have demonstrated that CXCR4 antagonists could reduce the inhibitory effect of immunosuppressive cells on Teff cells and increase T-cell sensitivity to tumor antigens." (PMID 33746989, 2021). "Therefore, there is potential to upregulate the expression of CXCR4 for promoting the migration of stem cells to tumor sites." (PMID 34069607, 2021). "We also observed that CXCR4 mainly expressed inside the tumor region but rarely in the peri-tumor." (PMID 34676245, 2021). "Interestingly, elevated CXCR4 promoting a conducive tumor microenvironment through upregulation of stress activated kinase signaling is consistent with a weak M12-like signature in our network and with better survival when expressed less abundantly." (PMID 34007962, 2021).
tumor (continued). "Moreover, tumors highly express CXCL12 (SDF1α), the ligand for CXCR4 (CD184), a homeostatic chemokine receptor found to be mostly involved in attracting immune cells within the tumor tissue, contributing to an immunosuppressive milieu." (PMID 34504486, 2021). "On the other hand, the tumor/muscle ratios of tumor receptor-targeting peptides, including the αvβ3 integrin-derivative 68Ga-c(RGDyK) and the CXCR4-derivative 68Ga-CPCR4-2 are higher (9.30 ± 3.90 and 16.6 ± 3.80, respectively, at 60 min) than that of 67Ga-NOTA-KV6 (5.05 ± 1.51 at 120 min)." (PMID 34069243, 2021). "Furthermore, the CXCL12/CXCR4 axis activates multiple signaling pathways to promote tumor cell proliferation, invasion, distant metastasis, and inhibit apoptosis." (PMID 34447750, 2021). "CXCL12 affects tumor cell biology via 1) direct stimulation of signaling pathways that promote cancer cell growth, metastasis, and angiogenesis; 2) indirect effects, including the recruitment of CXCR4/CXCR7-positive cancer cells to CXCL12-expressing organs." (PMID 34540690, 2021). "Tumour cells expressing the receptor for CXCL12 (CXCR4), which is involved in metastasis, were strongly reduced, reflecting the effect of hypoxia on tumour cells, whereas CXCR4 expression was not affected in CD45+ cells or in the endothelial cell‐enriched population." (PMID 33624446, 2021). "In osteosarcoma, CXCR4+MDSCs migrate tumor tissues toward an SDF-1 gradient, which could inhibit CTL expansion and result in resistance to ICB." (PMID 35003065, 2021). "The immune suppression caused by FAP+ CAF is mediated by the CXCL12 receptor CXCR4 that excludes T cells from the tumor." (PMID 34094963, 2021). "Both the lung and the bone marrow express high CXCL12 levels, and CXCL12 gradients may be responsible for long-distance attraction and binding to CXCR4-positive tumor cells." (PMID 33919988, 2021). "First, we categorized clustered data into tumor and stromal populations using a panel of markers for each (epithelial: AQP1, AQP2, EPCAM; endothelial: PLVAP, CD31, CD34; fibroblast: PDGFRα, PDGFRβ; immune: CD45; tumor cell: CXCR4, VIM, KRT18, PAX8, PAX2, CA9, CD10)." (PMID 34884982, 2021). "Interestingly, at least one study indicated that the cytoplasmic expression of CXCR4 is correlated with tumor burden and the metastatic load of certain cancers." (PMID 33966046, 2021). "Finally, to investigate the specific accumulation of ADM3100 on the CXCR4+ tumor cells, we radiolabeled it with 64Cu." (PMID 33414415, 2021). "In brief, especially CXCR2 and CXCR4 mediate tumor angiogenesis." (PMID 34203660, 2021). "The chemokine CXCL12 released from tumor cells and CAFs may suppress the infiltration of T lymphocytes through a mechanism called chemorepulsion mediated by CXCR4, which is the receptor for CXCL12 and also expressed on T lymphocytes." (PMID 34293030, 2021). "This revealed that the intertwining between CXCL12, mainly expressed by nerve tissue in the SACC specimens with PNI and CXCR4, strongly expressed by tumour cells at nerve invasion frontier might offer favourable terms for the initiation of PNI in SACC." (PMID 34170080, 2021). "CXCL12/CXCR4 mediates the B regulatory cells recruitment to the tumor inhibiting T cell activity." (PMID 33937018, 2021). "Indeed, Ac-KLF5 transactivates the CXCL12/CXCR4 chemokine axis, IL-11 cytokine signaling, and likely other paracrine molecules in tumor cells, as revealed by RNA-Seq, ChIP-Seq, and related analyses." (PMID 33731701, 2021). "CXCL12 (SDF-1α)/CXCR4 signaling is upregulated in radiation-induced EndoMT in tumor vasculature where it is required for tumor-associated macrophage recruitment, and knockdown of either of CXCL12’s receptors, CXCR4 and CXCR7, disrupts angiogenic sprouting in vitro." (PMID 34692672, 2021). "Meanwhile, silencing CXCR4 significantly reduced the migration of these tumor cells." (PMID 34093792, 2021).
tumor (continued). "Moreover, the expression levels of miR-186-5p and miR-548c-3p were lessened, whereas the CXCR4 protein level was raised in the tumor tissues of the lung metastasis model mice that were transplanted with circBACH2-overexpressed cells." (PMID 33875646, 2021). "This HIF-dependent activation of CXCR4 that is mediated by IL-33 may suggest a novel mechanism for the induction of tumor progression." (PMID 34298657, 2021). "Additionally, IFN-γ can contribute to metastasis through induction of CXCR4 on tumor cells and promotion of epithelial-to-mesenchymal transition." (PMID 34504657, 2021). "Of note, we have previously shown that Nanog regulates primordial germ cell migration through Cxcr4 in medaka fish, suggesting that Nanog-dependent tumor development may require CXCR4 expression." (PMID 34638956, 2021). "Thus, targeting the IL-33-enhanced-CXCR4 regulatory circuit attenuates tumor aggressiveness and provides a potential therapeutic option for improving the prognosis in HNSCC patients." (PMID 34298657, 2021). "In this study, MYD88 and CXCR4 tumor mutational status were examined and did not appear to impact response attainment, although the patient numbers are small." (PMID 33273682, 2021). "For this reason, several CXCR4 antagonists have already been tested as potential anti-tumor agents." (PMID 34833360, 2021). "These actions may be mediated by direct binding CXCR4 expressed by tumor vessels, or by promoting the recruitment of leukocytes." (PMID 34200145, 2021). "Indeed, CXCR4 overexpression has been shown in over 20 human tumor types, and correlated with tumor aggressiveness and higher probability of recurrence." (PMID 34793563, 2021). "Interestingly, these undifferentiated CXCR4-null tumors had higher tumor cellularity, with less ECM deposition and fewer stromal cells present, indicating that CXCR4 can be critical to the desmoplastic response in PDAC." (PMID 34298706, 2021). "In addition, the inhibitors of rhosin suppressed RHAMM and CXCR4 expression, leading to inhibition of tumor metastasis." (PMID 33406809, 2021). "Meanwhile, CXCR4 inhibitor (AMD3100) suppressed tumor cell migration as Salmonella." (PMID 34220311, 2021). "Our data suggest that NRN1 exhibits a tumor-promoting effect in RCC in collaboration with CXCR4." (PMID 34804954, 2021). "Therefore, the screening of antagonists targeting the CXCL12/CXCR4 signaling pathway is a promising target for tumor therapy." (PMID 34447750, 2021). "Furthermore, in breast cancer and colon cancer, aberrant production and signalling of SDF-1 has been reported to exert EMT-like effects via binding to its receptor, CXCR4 (seven-transmembrane G protein-coupled receptors) in the tumour cell membrane." (PMID 33637678, 2021). "In addition, a recent study using pancreatic patient samples revealed a mobilization of CD8+ T cells in juxtatumoral areas following CXCR4 inhibition and increased tumor cell killing when combined with PD-L1 inhibition." (PMID 35008248, 2021). "Although many underlying mechanisms and their implications for disease progression are not elucidated yet, most tumors import a worsening prognosis with increasing CXCR4 expression, which is known to play an important role in both tumor cell proliferation and metastasis." (PMID 34885030, 2021). "In addition, stimulation of the CXCL12/CXCR4 signaling contributes to organ colonization with blood circulating tumor cells in HCC." (PMID 34386499, 2021). "Therefore, inhibiting CXCR4 expression in DLBCL tumor cells can prevent their migration and invasion." (PMID 34093792, 2021). "Furthermore, we evaluated the expression of CXCL12 and its receptor CXCR4 as well as some XBP1 pathway molecules in tumor cells under different culture condition." (PMID 34093792, 2021). "Thus, CXCR4 and its ligands not only prevent T cells from migrating from the stroma to the malignant cells, but also appear to be involved in tumor cell migration and invasiveness." (PMID 34203869, 2021).
tumor (continued). "In addition, enhanced CXCL12/CXCR4 signaling can induce cells to secrete growth factors and cytokines to create a beneficial microenvironment for tumor growth." (PMID 33962657, 2021). "Moreover, chimeric antigen receptor (CAR) NK cells overexpressing CXCR4 were shown effective against tumours." (PMID 34709764, 2021). "Although CXCR4 is widely expressed not only by immune cells but also various tissue cells including tumor cells and stromal cells, recent clinical studies have shown that the CXCR4 inhibitors including BL-8040, balixafortide, and LY2510924 are safe and tolerable in humans." (PMID 34885241, 2021). "T-cell exclusion could be mediated by fugetaxis—an active movement of T cells away from a high concentration of CXCL12 coating the tumor cells —or T-cell apoptosis similar to that observed by the engagement of CXCR4 with the gp120 coat protein of HIV." (PMID 35008248, 2021). "Activation of the CXCR4/CXCL12 pathway is associated with the formation of an immunosuppressive tumor microenvironment, and X4P-001 (a CXCR4 antagonist) can block excessive activation of this pathway to reverse tumor immune escape." (PMID 33746989, 2021). "CXCR4 is abundantly present in cells assigned to the “macrophage” and “myeloid cell” signatures, as well as in “vascular cells” and “neoplastic cells”, which is in line with the various roles of this receptor in diverse tumor-related processes." (PMID 35008294, 2021). "Blocking the CXCL12/CXCR4 signaling axis may inhibit tumor growth and provide new ideas for immunotherapy." (PMID 33894748, 2021). "Moreover, it facilitates metastasis of CXCR4-expressing tumor cells to mesenchymal stromal tissues with high SDF-1α expression such as liver, bone marrow, lungs and lymph nodes." (PMID 34683912, 2021). "In the tumor tissues of the lung metastasis model mice transplanted with circBACH2-knockdown cells, the expression levels of miR-186-5p and miR-548c-3p were elevated, whereas the CXCR4 protein level was declined." (PMID 33875646, 2021). "As the CXCR4/CXCL12 axis was well known for chemotaxis of tumor cells in bone metastasis, we co-cultured TNBC cell lines with reduced CTNND1 together with fibroblasts, osteoblasts and CXCL12 cytokine, respectively, as CXCL12 was mainly produced by fibroblasts and osteoblasts in bone." (PMID 34830862, 2021). "Recent research has shown that the SDF-1/CXCR4 may additionally promote tumour EMT by way of activating the β-catenin signalling pathway in breast and colon most cancers." (PMID 33637678, 2021). "In addition, increasing evidence indicates that the CXCL12/CXCR4 axis plays an important role in the biological processes of tumor cells." (PMID 33710803, 2021). "We demonstrated a differential expression of the axis components between malignancy and normal adrenal, showing a reduced expression of CXCL12 protein in the tumor compared with the normal adrenocortex, and confirming the CXCR4 and CXCR7 expression as reported in the literature." (PMID 34834449, 2021). "We previously reported that CXCR7/AKCR3 may act as a decoy receptor for CXCL12 that counteract CXCR4-mediated LNCaP cell migration, a process that promote tumor metastasis." (PMID 33808801, 2021). "Moreover, the CXCL12 produced by tumor cells attracts CXCR4+ Treg and pro-tumorigenic myeloid-derived suppressor cells, further promoting tumor progression." (PMID 33805447, 2021). "As a part of the homing cascade, SDF-1 from MSCs and their terminal differentiation, osteoblasts, interacts with its receptor CXCR4, which is highly expressed by bone metastasizing lineages like breast and prostate, facilitating tumour cells to colonize and survive in the bone microenvironment." (PMID 35006432, 2021). "Moreover, CXCR4 is presented on circulating tumor cells released from tumors into the peripheral blood, which induces their spread to CXCL12-positive distant sites." (PMID 34203877, 2021).
tumor (continued). "Results from TME research have indicated that hypoxia stimulation may improve the migration of stem cells to tumor through the C-X-C chemokine receptor type 4 (CXCR4)/stromal cell-derived factor-1α (SDF-1α) axis." (PMID 34069607, 2021). "In addition, AMD3100 has been labeled with copper 64 to visualize CXCR4-positive tumor cells in vivo and can be used to guide and monitor anti-CXCR4 tumor treatment." (PMID 33710803, 2021). "We investigated by flow cytometry whether TNC influenced CD8 TIL function in vivo through CXCL12, by blocking CXCR4 with AMD (for 2 weeks) in tumor‐bearing mice in the 4‐week model (Figs EV2 and EV4A–H)." (PMID 33988305, 2021). "In addition, the JAK2/STAT3 pathway is involved in the SDF-1/CXCR4 interaction promoting mesenchymal stem cell migration in response to the tumor microenvironment." (PMID 34124069, 2021). "There are many reports on the effect of CXCR4 gene silencing on tumor biological characteristics." (PMID 35111484, 2021). "Thus, in vivo results confirmed that CXCR4 overexpression promoted tumor growth of HCC in mice by activating the c‐Met signaling pathway." (PMID 34555268, 2021). "Therefore, an analysis of CXCR4 signaling is essential to elucidate the mechanism of tumor metastasis." (PMID 34615896, 2021). "Indeed, genetic CXCL12 deletion or pharmacological inhibition of CXCR4 partially prevents BrCa and PrCa metastasis to lungs and bones as well as early steps of intraosseous tumor growth." (PMID 34064859, 2021). "An increase in the expression of CXCL12 in the brain after exposure to X-ray radiation may affect the implanted tumor cells, leading to an increase in the expression of CXCR4 in tumor cells." (PMID 34764346, 2021). "Apart from constituting an HSC mobilising agent, both preclinical and clinical studies have suggested that AMD3100 and other CXCR4 antagonists exhibit anticancer activity, inhibiting tumor growth and metastasis as well as counteracting an immunosuppressive intratumoral microenvironment." (PMID 34575965, 2021). "Furthermore, we investigated how vascular CXCR4 reflects whole-tumor expression through comparison with imaging data produced by a tumor-penetrating CXCR4-dedicated PET tracer, [18F]MCFB." (PMID 34793563, 2021). "Moreover, it was reported that high levels of CXCL12 (SDF-1) are secreted by MSCs that regulate the migration and invasion of CXCR4-expressing tumor cells." (PMID 33472580, 2021). "Conclusions concerning the prognostic value of vascular CXCR4 in our tumor models are challenging." (PMID 34793563, 2021). "In addition, CXCR4 plays an important role in inflammation with its ligand CXCL12 and associates with pathological processes such as tumor proliferation, angiogenesis, and metastasis." (PMID 34804954, 2021). "The CXCR4 in tumors correlates with tumor size, metastasis, and prognosis." (PMID 34220311, 2021). "Interestingly, activation of the SDF-1 CXCR4 axis results in tumor mediated secretion of CXCL16 to recruit CXCR6 positive mesenchymal stem cells to the tumor microenvironment." (PMID 34503118, 2021). "Thus, we conclude that TNC plays an important role in regulating macrophages and CD8 TIL through CXCL12/CXCR4 signaling thereby impairing tumor cell killing and promoting tumor growth." (PMID 33988305, 2021). "Likewise, blocking CXCL12/CXCR4 using AMD3100 significantly inhibited tumor growth and metastasis, and the combination of AMD3100 and anti-PD-1 further reduced tumor growth and metastasis." (PMID 34911533, 2021). "CXCR4 is a chemokine receptor responsible for MSC tumor tropism." (PMID 34068264, 2021). "Another mechanism of tumor recurrence is the resistance to TMZ treatment which could be promoted by the upregulation of FOXM1 mediated through CXCR4/CXCL12." (PMID 34203660, 2021).